ADAMTS8 (ADAM metallopeptidase with thrombospondin type 1 motif 8)
Diseases named in the same sentence as ADAMTS8 in open-access papers (continued):
Sharing a sentence is not in itself a finding about the gene and the disease.
intervertebral disc degeneration (1 paper, 2020). "Incorporating the transcriptome data analysis results, we hypothesize that sIL-13Rα2-Fc can maintain a dynamic balance in the ECM and delay intervertebral disc degeneration by inhibiting Adamts8-mediated ECM degradation." (PMID 32855969, 2020). "sIL-13Rα2-Fc promoted anabolism of the ECM and increased the levels of ECM components by inhibiting the expression of Adamts8, thus maintaining the dynamic equilibrium of the ECM and ultimately delaying intervertebral disc degeneration." (PMID 32855969, 2020). "Adamts8 may participate in the degradation of ECM components such as GAG and HA and lead to an imbalance in the ECM of the intervertebral disc, resulting in intervertebral disc degeneration." (PMID 32855969, 2020).
liver cancer (1 paper, 2020). An epithelial or non-epithelial malignant neoplasm that arises from the liver. "ADAMTS8 is underexpressed in liver cancer and affects its progression by targeting the ERK signaling pathway." (PMID 32884571, 2020).
melanoma (1 paper, 2022). A malignant, usually aggressive tumor composed of atypical, neoplastic melanocytes. "The GSEA data favored the role of ADAMTS8 in enhancing the metastasis of melanoma." (PMID 35743687, 2022).
metastatic tumors (1 paper, 2012). "They found that ADAM8 was expressed significantly higher in metastatic tumors as well as identifying several proteinases of the ADAM-family (ADAM9, ADAM17, ADAM28, ADAMTS1, ADAMTS8 and ADAMTS15) -including ADAM8- which are HNSCC associated." (PMID 22369429, 2012).
Myocardial fibrosis (1 paper, 2022). "ADAMTS8 overexpression in MI rats impaired cardiac function and promoted myocardial fibrosis at 28 days post-MI in vivo." (PMID 35224040, 2022). "Therefore, this study aimed to explore the effect and mechanism of ADAMTS8 in myocardial fibrosis after injury or stress." (PMID 35224040, 2022). "However, the effect of ADAMTS8 in myocardial fibrosis has not been thoroughly investigated." (PMID 35224040, 2022).
myocardial infarction (1 paper, 2022). Gross necrosis of the myocardium, as a result of interruption of the blood supply to the area, as in coronary thrombosis. "However, the specific role of ADAMTS8 in cardiac fibrosis caused by myocardial infarction or pressure overload is yet unclear." (PMID 35224040, 2022). "Compared with the rats injected with positive control virus, the cardiac function of the rats injected with overexpressed ADAMTS8 adenovirus was significantly decreased after myocardial infarction." (PMID 35224040, 2022). "Adenovirus-mediated overexpression of ADAMTS8 through cardiac in situ injection aggravated cardiac fibrosis and impaired cardiac function in the myocardial infarction rat model." (PMID 35224040, 2022). "Therefore, the combined findings in vivo and in vitro indicated that the ADAMTS8 overexpression in the infarct boundary zone after myocardial infarction was one of the reasons for CFs enhancement, which lead to cardiac dysfunction and remodeling after myocardial infarction." (PMID 35224040, 2022).
parasite infections (1 paper, 2022). "Additionally, we found that mebendazole, which is used to treat parasite infections, suppressed the expression of ADAMTS8 and ameliorated cardiac fibrosis induced by MI and TAC." (PMID 35224040, 2022).
rectal cancer (1 paper, 2025). A primary or metastatic malignant neoplasm that affects the rectum. "Our study identifies ADAMTS8 as potentially associated with a histopathological subtype of rectal cancer." (PMID 40650042, 2025). "Nonetheless, the exact molecular mechanisms behind ADAMTS8-mediated progression of vascular invasion in RC require further investigation in a larger cohort of patients with vascular invasion-positive rectal cancer." (PMID 40650042, 2025). "To further investigate the role of ADAMTS8 deregulated expression in rectal cancer pathogenesis, we analyzed correlations between ADAMTS8 mRNA expression and the expression of the other 40 preselected genes in our cohort." (PMID 40650042, 2025).
septal defects (1 paper, 2006). "ADAM genes identified in this study have previously been associated with ventricular septal defects and valvular defects (ADAM19), fibrotic eye disease (ADAMTS9), disrupting angiogenesis (ADAMTS8), and cell adhesion (ADAM 28)." (PMID 16948840, 2006).
squamous cell carcinoma (1 paper, 2016). A carcinoma arising from squamous epithelial cells. "The original data from TCGA verified that ADAMTS8, DMBT1 and DOCK8 were down-regulated in adenocarcinoma and squamous cell carcinoma, whereas RSPO3 was overexpressed in adenocarcinoma and down-regulated in squamous cell carcinoma." (PMID 27980454, 2016). "We found that RSPO3, ADAMTS8, DMBT1 and DOCK8 were all downregulated in squamous cell carcinoma tissues compared to non-cancerous lung tissues, whereas STMN2, TUSC3 and C8orf22 were upregulated in squamous cell carcinoma (all P < 0.001)." (PMID 27980454, 2016). "Only ADAMTS8 was related to the TNM stage (t = 0.041, P = 0.032) in squamous cell carcinoma." (PMID 27980454, 2016).
status epilepticus (1 paper, 2021). Status epilepticus is defined as a continuous seizure lasting more than 30 min, or two or more seizures without full recovery of consciousness between any of them. "Following status epilepticus, transcripts of matrix metalloproteinases such as MMP3, ADAMTS5, ADAMTS8, and ADAMTS9 were induced." (PMID 35185464, 2021).
thyroid cancer (1 paper, 2016). "Moreover, the decrease in ADAMTS8 expression has been documented in some cancers that ADAMTS8 shows high frequency of promoter methylation in brain, lung, and thyroid cancer suggesting that the epigenetic silencing of ADAMTS8 may be involved in tumorigenesis." (PMID 27493958, 2016).
tumor (33 papers, 2004 to 2025). "It has been identified as a novel tumor suppressor gene as high levels of ADAMTS8 is associated with poor prognosis among breast cancer patients due to its role in promoting metastasis." (PMID 34131102, 2021). "Specifically, knockdown of OIP5-AS1 caused a decrease in tumor tissue volume, and relative ADAMTS8 levels were significantly reduced upon OIP5-AS1 knockdown." (PMID 34131102, 2021). "Indeed, several studies have showed that anti-tumor effects of ADAMTS8 and ADAMTS12 are closely associated with the suppression of ERK signaling." (PMID 28145888, 2017). "This silencing is significant because ADAMTS8 plays a role in inhibiting tumor cell growth and motility by antagonizing the EGFR-MEK-ERK signaling pathway, which is crucial for cancer cell proliferation and survival." (PMID 40650042, 2025). "ADAMTS8 and two other members of its gene family have previously been recognized as anti-angiogenic agents, drawing attention to them as potential tumor inhibitors." (PMID 40650042, 2025). "Restoration of ADAMTS8 expression has been shown to suppress tumor cell clonogenicity and induce apoptosis, highlighting its potential as a therapeutic target and biomarker in CRC." (PMID 40650042, 2025). "Beyond CRC, ADAMTS8 is also recognized for its tumor-suppressive and anti-angiogenic roles across various cancer types." (PMID 40650042, 2025). "ITGA8 and ADAMTS8 were downregulated in tumor tissues, whereas FERMT1, CTSV, CPS1, ENTPD2, SERPINB5, and LYPD3 were upregulated in tumor tissues." (PMID 35557945, 2022). "The expression levels of ADAMTS8 were lower in tumor parts in our clinical cohorts, the TCGA and seven other cohorts, but the relationships were not lymph node metastasis or stage-dependent." (PMID 35743687, 2022). "The only immune cell that was positively correlated with ADAMTS8 was Tfh; this association helped to develop or support the recruitment sites of CD8+T cells, NK cells, and macrophages, while supporting the anti-tumor antibody response of B cells." (PMID 36686480, 2022). "To further assess the impact of ADAMTS8, we utilized the data of the TCGA cohort and discovered a lower level of ADAMTS8 in tumor parts and other members of the ADAMTS family, except for ADAMTS10." (PMID 35743687, 2022). "We observed that higher expression of OIP5-AS1 and ADAMTS8 correlated with tumor size, lymph node metastasis, and TNM stage." (PMID 34131102, 2021). "In mice that received OIP5-AS1-overexpressing K1 cells, tumor weight and volume were significantly increased when compared to the negative control, and this increase was lost in tumors from mice that received ADAMTS8 knockdown cells." (PMID 34131102, 2021). "In the Okayama Lung dataset, the alternation of ADAMTS8, METTL7A, MYH10 and PRC1 were associated with tumor grade, implicating vital roles of these genes in the carcinogenesis or progression of LUAD." (PMID 31333911, 2019). "ADAMTS1, as well as ADAMTS8 and 15, all promote tumor growth and metastasis in the MMTV-PyMT model, and predict survival of human basal breast cancer." (PMID 27542270, 2016). "IHC data indicated the presence of ADAMTS-8 protein in the normal cerebellum and lower levels of protein in the majority (77%) of tumours tested." (PMID 16570050, 2006). "Immunohistochemistry and Western analysis indicated downregulation of ADAMTS-8 protein in >77% tumours." (PMID 16570050, 2006). "ADAMTS-8 protein in neoplastic cells was downregulated in the majority of tumours (27 out of 35, 77%) compared to cerebellum or uninvolved ‘normal’ non-neoplastic brain present within some tumour sections." (PMID 16570050, 2006). "Contrarily, ADAMTS8 acts as a tumour suppressor in CRC by inactivating the Wnt pathway." (PMID 38948119, 2024). "Similarly, downregulated genes identified in Cluster 1 have been previously associated with more aggressive tumor characteristics and higher tumor grade; these include RNF39, ADAMTS8, SLC25A42, ST3GAL5, and ZBED3." (PMID 39766155, 2024).
tumor (continued). "Meanwhile, ADAMTS8 exhibited an inhibitory influence on tumor proliferation and invasion 47-49." (PMID 37056938, 2023). "ADAMTS 8 is a tumour suppressor and ADAMTS 5 contributes to tumorigenesis." (PMID 36982551, 2023). "Interestingly, the tumor suppressor ADAM metallopeptidase with thrombospondin type 1 motif 8 (Adamts8) was also upregulated." (PMID 35565312, 2022). "ADAMTS8 has been reported to function as a tumor suppressor gene in various solid tumors." (PMID 35557945, 2022). "In addition, mice that received OIP5-AS1 knockdown TPC-1 cells showed significantly lower tumor weight and volume, this effect was restored upon ADAMTS8 overexpression." (PMID 34131102, 2021). "For example the predominant role of ADAMTS-8 may be antiangiogenesis, necessitating silencing in tumours, whereas the predominant role for ADAMTS-4 and TS-5 may be ECM degradation necessitating up-regulation." (PMID 16570050, 2006). "The antibody used in this study recognises a binding site within the prodomain and Western data revealed a 98 kDa ADAMTS-8 band common to both tumour and normal brain, consistent with the size of the full-length secreted protein after removal of the signal peptide." (PMID 16570050, 2006). "Furthermore, ADAMTS8 and SLC25A42 encode for proteins with strong antiangiogenic effects and antiproliferative properties, respectively, with decreased expression associated with increased tumor viability and proliferation." (PMID 39766155, 2024). "However, studies have suggested that the tumor-suppressive effects of ADAMTSs are linked to the deactivation of proliferation or invasion pathways, including inhibition of the ERK pathway by ADAMTS8, ADAMTS12, and ADAMTS15; and of the AKT/mTOR pathway by ADAMTS9." (PMID 27542224, 2016). "The tumor-suppressive mechanism of some ADAMTS family members, such as ADAMTS8 and ADAMTS12, is manifested by antagonizing ERK signaling, and the ERK/P38 MAPK signaling pathway inhibits tumor growth in colon adenocarcinoma." (PMID 38482210, 2024). "In the HPA database, protein expressions of the seven genes (ADAMTS8, CCR2, CYSLTR2, FAM129C, FCER1A, GAPT, PKHD1L1, and ZNF831) were markedly low in tumor tissues with less intense antibody staining and fewer stained cells in LUAD." (PMID 36033829, 2022). "Among these genes, ITGA8 and ADAMTS8 were downregulated in LUAD tissues and functioned as tumor suppressor genes, whereas the remaining genes were oncogenes." (PMID 35557945, 2022). "Overexpression of ADAMTS8 was shown to reduce β-catenin levels, as well as the phosphorylation of GSK3β, leading to reduced CRC cell invasion and migration in vitro and reduced tumour growth in vivo." (PMID 38948119, 2024). "Even more, Kaplan-Meier survival curves of progression-free survival (PFS) demonstrated inferior survival probabilities in patients with high tumor expression of PXDNL (p=0.0001) and SDC1 (p<0.0001) and low tumor expression of FBLN1 (p=0.0087), FBLN5 (p=0.026) and ADAMTS8 (p<0.0001)." (PMID 37056938, 2023). "Two mucinous type metastatic tumours of gastrointestinal origin showed strong staining (+++) for ADAMTS-8, although notably, neither of these cases gave a specific band in the Western analysis, which could be due to the lower proportion of ADAMTS-8 expressing cells within these samples." (PMID 16570050, 2006). "However, other documented forms (79 and 64 kDa) of ADAMTS-8, which retain antiangiogenic activity after proteolytic cleavage, may be present in normal and tumour brain tissues, would not be detected in the present study." (PMID 16570050, 2006). "Angiogenesis is a critical event during implantation and tumour invasion, and ADAMTS-1 and -8 have been assigned this function in several kinds of tumours, but the expression and regulation of ADAMTS-8 in reproductive tissues have not been reported." (PMID 23947778, 2013).
cancer (24 papers, 2006 to 2025). A tumor composed of atypical neoplastic, often pleomorphic cells that invade other tissues. "A disintegrin and metallopeptidase with thrombospondin motifs 8 (ADAMTS8) has been linked to several cancer types." (PMID 35743687, 2022). "ADAMTS8 inactivation by epigenetic modifications has been reported in various tumors, and the dysregulation of ADAMTS8 expression is associated with poor clinical outcomes, cancer cell invasion, and metastasis." (PMID 40323963, 2025). "Reduced expression of ADAMTS8 is frequently associated with cancer cell invasion and metastasis." (PMID 34687701, 2021). "We found that in the case of the ALT high TEL high phenotype, genes TRIP13, TPX2, and MCM7 were upregulated in eight cancer types and ADAMTS8 in seven cancer types was downregulated." (PMID 38763334, 2024). "Despite the fact that ADAMTS8 has been mainly reported to be downregulated in cancer, BC patients with low levels of ADAMTS15, in combination with high ADAMTS8 expression, showed the worst prolonged relapse-free survival." (PMID 38948119, 2024). "Although ADAMTS-8 revealed a predominantly cytoplasmic expression profile in carcinoma cells, stromal expression adjacent to the evaluated in situ and invasion areas was also found." (PMID 39682243, 2024). "ADAMTS8 serves as a suppressor or oncogene in numerous cancers." (PMID 37214471, 2023). "Only in KRAS-mut cancers was a single family member, ADAMTS8, conserved." (PMID 36612014, 2022). "Cancer cell lines including HCC827 (del E746-A750 in exon 19), HCC2279 (del E746-A750 in exon 19) and HCC4006 (del E746-A750 in exon 19) have higher levels of ADAMTS8 expression than in TKI-resistant cancer cell lines (H1650 (del E746-A750 in exon 19) and H1975 (L858R in exon 21))." (PMID 35743687, 2022). "ADAMTS8, previously referred to as METH-2, is one such “orphan protease” that is predominantly expressed in the lung and heart and is reported to be downregulated via promoter hypermethylation in a variety of cancers." (PMID 34687701, 2021). "Downregulated ADAMTS8 in some cancers including NSCLC is associated with poorer prognosis." (PMID 31333911, 2019). "Several reports have emerged about ADAMTS8 being down-regulated or silenced in various cancers." (PMID 24213506, 2012). "Our data are consistent with other reports of ADAMTS-8 downregulation in cancers, suggesting there may be opposing physiological roles for individual ADAMTS family members in carcinogenesis." (PMID 16570050, 2006). "This approach allowed us to identify gene transcripts that increased in cancer such as MMP11 (increase rank by 223 positions) and gene transcripts with lower expression in cancer such as ADAMTS8 (decrease rank by 196 positions)." (PMID 34732773, 2021). "Out of several cancer cell lines probed so far, only SW480—a colon carcinoma cell line expressed ADAMTS8." (PMID 24213506, 2012). "We found seven upregulated genes (MCM10, RAD51-associated protein 1 (RAD51AP1), KIF2C, Y_RNA, FAM64A, CDC6, and CDCA8) and six downregulated genes (ADAMTS8, ATP1A2, MYH1, OGN, OMD, and ZBTB16) in at least two phenotypes containing either ALT high/middle or TEL high/middle regardless the cancer type." (PMID 38763334, 2024). "Just like in any other carcinoma, Ca Pancreas cells mobilize themselves through the surrounding stroma via proteases and, during our review, it was noted that ADAMTS1, ADAMTS 8, ADAMTS 9, and ADAMTS 18 were highly expressed by them and associated with early nodal, as well as distant metastasis." (PMID 37623681, 2023).
adenocarcinoma (1 paper, 2016). A common cancer characterized by the presence of malignant glandular cells. "The upregulated expression of RSPO3, ADAMTS8 and DOCK8 was associated with the overall survival (all P < 0.05) and disease-free survival of adenocarcinoma patients (all P < 0.05), which indicated that RSPO3, ADAMTS8 and DOCK8 might influence the prognosis of adenocarcinoma." (PMID 27980454, 2016).
ADAMTS8 also shares sentences with these, for which no sentence is quoted: lung squamous cell carcinoma (2 papers); medulloblastoma (2); pancreatic cancer (2); acute aortic dissection (1); anaplastic gliomas (1); atherosclerosis (1); Barrett esophagus (1); bladder cancer (1); connective tissue disease (1); esophageal cancer (1); infection (1); meningioma (1); papillary thyroid cancer (1); renal cell carcinoma (1); respiratory diseases (1); Right ventricular hypertrophy (1); small cell lung carcinoma (1).